SIRPA (signal regulatory protein alpha)
Diseases named in the same sentence as SIRPA in open-access papers (continued):
Sharing a sentence is not in itself a finding about the gene and the disease.
Obesity (2 papers, 2025 to 2026). Accumulation of substantial excess body fat. "Altogether, these results indicated that Sirpα deletion in macrophages caused improved glucose disposal, increased energy expenditure, reduced weight gain and decreased “pro-obesity” miRNAs in diet-induced obesity." (PMID 40016734, 2025). "Consistently, we observed that SIRPα deficiency in macrophages protects mice from diet-induced obesity." (PMID 40016734, 2025). "Consistent with this, SIRPα-deficient mice exhibited a reduction in vWAT-Exos and displayed greater resistance to obesity." (PMID 40016734, 2025). "Genetic deletion of muscle SIRPα protected against obesity and improved intracellular insulin signaling in muscle and adipose tissue, with reduced intramuscular fat deposition when compared with flox mice on HFD." (PMID 41657313, 2026). "In the obesity-induced diabetic mice, serum SIRPα increased." (PMID 41657313, 2026). "Nevertheless, loss of SIRPα had no impact on macrophage infiltration and polarization in the context of obesity." (PMID 40016734, 2025).
ovarian tumors (2 papers, 2021 to 2022). "CD47 is a cell surface antigen highly expressed in ovarian tumors that functions equally as a macrophage “don’t eat me” signal enabling malignant cells to escape cell phagocytosis and thus detection by the immune system, by interacting with macrophage’ surface signal-regulatory protein-α (SIRPα)." (PMID 35211124, 2022). "While thrombospondin-1 (TSP-1) was mentioned for the first time two decades ago when elevated TSP-1 mRNA levels were found within ovarian tumors, most efforts focused on disrupting CD47/SIRPα up to now, in the purpose of promoting cancer cell phagocytosis." (PMID 34638503, 2021).
polycythemia (2 papers, 2023). Abnormally high mass or concentration of red blood cells in the blood, either due to an increase in erythropoiesis or a decrease in plasma volume. "The polycythemia phenotype was restored by intercepting CD47-SIRPα through either anti-CD47 treatment or loss of the inhibitory SIRPα-signal in a PV mouse model." (PMID 38111586, 2023). "Our results show that blocking CD47-SIRPα in a PV mouse model due to either anti-CD47 treatment or loss of the inhibitory SIRPα-signal corrects the polycythemia phenotype." (PMID 37095207, 2023). "Our results show that CD47-SIRPα-signaling in a PV mouse model due to either anti-CD47 treatment or loss of the inhibitory SIRPα-signal corrects the polycythemia phenotype." (PMID 37095207, 2023).
schizophrenia (2 papers, 2020 to 2021). A major psychotic disorder characterized by abnormalities in the perception or expression of reality. "The agonism of SIRPα could be a potential strategy to suppress synaptic pathology in schizophrenia." (PMID 34063598, 2021).
synovial sarcoma (2 papers, 2021). "Many pediatric tumors, including bone sarcomas and synovial sarcomas, demonstrate surface expression of SIRPα on a par with that of CD47, suggesting that the interaction between the two is likely relevant." (PMID 33717062, 2021).
Type 1 Diabetes (2 papers, 2018 to 2019). "SIRPα has been shown to have a possible role in auto-immunity having been found to be a risk loci in individuals with Type 1 Diabetes, and Crohn's patients have increased SIRPα/β+CD11C+DCs in the mesenteric lymph nodes and inflamed intestinal mucosa." (PMID 30568660, 2018). "Given that this then enhances the propensity of the cells to resist the effects of cytotoxic insults, these results suggest that decreases in STAT6 and SIRPα could contribute to beta cell demise during the progression of type 1 diabetes in susceptible individuals." (PMID 30338340, 2019).
acute lung injury (1 paper, 2022). A condition of lung damage that is characterized by bilateral pulmonary infiltrates (pulmonary edema) rich in neutrophils, and in the absence of clinical heart failure. "Soluble signal regulatory protein-alpha (SIRP-alpha) is elevated in bronchoalveolar lavage (BAL) of mice with lipopolysaccharides (LPS)-induced acute lung injury (ALI)." (PMID 35634325, 2022).
adenoma (1 paper, 2020). A neoplasm arising from the epithelium. "In particular, the mRNA levels of Sirpα in TAMs were positively correlated with the weight of spontaneous adenomas in APCmin+/- mice." (PMID 32296015, 2020). "We confirmed that the levels of TAM Sirpα were positively correlated with the weight of adenomas in APCmin+/− mice." (PMID 32296015, 2020).
allergic asthma (1 paper, 2024). A asthma with a basis in a pathological type I hypersensitivity reaction. "Overall, our results indicate that targeting SIRPα could be a promising therapeutic strategy for allergic asthma." (PMID 39160226, 2024). "Here, we provide a proof of concept that engagement of SIRPα via its ligand CD47 inhibits ILC2 activation and holds promise for therapeutic intervention in allergic asthma." (PMID 39160226, 2024).
allergic disease (1 paper, 2024). An immune response that occurs following re-exposure to an innocuous antigen, and that requires the presence of existing antibodies against that antigen. "To further confirm that SIRPα deficiency exacerbates AHR, we employed a clinically relevant pulmonary inflammatory disease model using Alternaria alternata (A. alternata), a common fungus associated with allergic disease." (PMID 39160226, 2024).
amyloid (1 paper, 2021). "We found microglial SIRPα deficiency had little effect on the amyloid deposition, while it increased synapses loss and enhanced memory impairment in AD mice." (PMID 33795678, 2021).
Anxiety (1 paper, 2022). Intense feelings of nervousness, tension, or panic often arise in response to interpersonal stresses. "The results of the open-field test (OFT), tail suspension test (TST) and forced swim test (FST) showed that SIRPα-v Exos ameliorated depressive symptoms such as nervousness, anxiety and fear exhibited in mice after ICH." (PMID 36435797, 2022).
Arrhythmia (1 paper, 2024). Any cardiac rhythm other than the normal sinus rhythm. "Interestingly, the strongest correlation between subpopulation quantification and arrhythmia burden occurred with a previously undefined SIRPA+CD90−CD200+ population (r = 0.81)." (PMID 39196193, 2024). "Conversely, SIRPA+CD90−CD200− cells had a negative association with arrhythmia burden (r = −0.77)." (PMID 39196193, 2024). "Furthermore, by robustly phenotyping input cell doses and correlating these with the resultant arrhythmia burden, we identify SIRPA+CD90+CD200+ and SIRPA+CD90−CD200− cells as populations of arrhythmogenic and potentially non-arrhythmogenic CMs, respectively." (PMID 39196193, 2024).
autoimmune uveitis (1 paper, 2021). An autoimmune form of uveitis (disease). "Overall our results demonstrated that CD47 plays an important role in development of autoimmune uveitis by promoting SIRPα+ DC maturation." (PMID 34093583, 2021). "Here we demonstrate that systemic expression of CD47 is essential in induction of autoimmune uveitis through promotion of development of SIRPα+ DCs which has a crucial role in the priming of autoreactive CD4+ T cells." (PMID 34093583, 2021).
B-cell acute lymphoblastic leukemia (1 paper, 2024). A neoplasm of lymphoblasts committed to the B-cell lineage, typically composed of small to medium-sized blast cells. "CD47 promotes cell adhesion by interacting with SIRPα which has been elucidated using an extracellular SIRPα-human Ig fusion protein to promote the CD47-mediated adhesion of B-cell acute lymphoblastic leukemia cells by inducing PI3K activation." (PMID 39039207, 2024).
Cerebral ischemia (1 paper, 2023). Restriction of arterial blood supply to the brain associated with insufficient oxygenation to support the metabolic requirements of the tissue. "Consistently, SIRPα deletion also confers robust neuroprotection at 24 h following cerebral ischemia." (PMID 37601043, 2023). "Thus, current evidence suggests that inhibiting SIRPα/CD47 signaling is neuroprotective following focal cerebral ischemia." (PMID 37601043, 2023).
Cholecystitis (1 paper, 2022). The presence of inflammatory changes in the gallbladder. "In addition, 4-methylumbelliferone (4MU), a cholecystitis drug, can disrupt the CD47/SIRPα axis by disturbing glioblastoma HA synthesis." (PMID 35410993, 2022).
CNS lymphoma (1 paper, 2020). "CNS lymphoma in mice was infiltrated by tumor-promoting M2-like macrophages expressing PD-1 and SIRPα." (PMID 32691208, 2020).
complication (1 paper, 2025). Any disease or disorder that occurs during the course of, or because of, another disease, treatment, or procedure. "SIRPα-defined alloresponse groups did not influence long-term clinical outcomes, including incidence of biliary complications, chronic rejection, and overall survival." (PMID 41245087, 2025).
epilepsy (1 paper, 2023). A brain disorder characterized by episodes of abnormally increased neuronal discharge resulting in transient episodes of sensory or motor neurological dysfunction, or psychic dysfunction. "By correlating co-expressed genes as well as immune cell ratios, we obtained genes with significant correlation with immune cell ratios (SIRPA, AKR1A1, LEP, ALDOA) that will be validated in epilepsy data at the single cell level in an attempt to find immune genes that link heart and brain tissue." (PMID 36776884, 2023).
follicular lymphoma (1 paper, 2019). Follicular lymphoma is a form of non-Hodgkin lymphoma characterized by a proliferation of B cells whose nodular structure of follicular architecture is preserved. "Using biopsy specimens from follicular lymphoma (FL), we identified three subsets (CD14+SIRPαhi, CD14−SIRPαlow, and CD14−SIRPαneg) of monocyte/macrophages (Mo/MΦ) based on CD14 and SIRPα expression." (PMID 31611550, 2019).
glaucoma (1 paper, 2012). Increased pressure in the eyeball due to obstruction of the outflow of aqueous humor. "Of these, only the CDKN2BAS and SIX1/SIX6 regions were significantly associated with glaucoma in the meta-analysis, although several other previously identified gene regions demonstrated suggestive associations including SALL1, LRP1B and SIRPA." (PMID 22570617, 2012).
gynecological cancers (1 paper, 2023). "Although magrolimab has been approved for the treatment of hematopoietic malignancies and several other CD47/SIRPα inhibitors have been assessed in many advanced cancers, clinical data about the efficacy of CD47/SIRPα inhibitors in patients with gynecological cancers are rare." (PMID 37368179, 2023).
head and neck cancer (1 paper, 2022). A primary or metastatic malignant neoplasm affecting the head and neck. "SIRPα combination therapy with CPI (ezabenlimab, pembrolizumab) yielded a study-level ORR of 18.8% to 20.0% in colorectal, endometrial, and head and neck cancer patients." (PMID 36439116, 2022). "Selective SIRPα combination therapy with CPIs (ezabenlimab, pembrolizumab) yielded study-level ORR of 18.8% to 20.0% in patients with recurrent colorectal, endometrial, and head and neck cancers." (PMID 36439116, 2022).
head and neck squamous cell carcinoma (1 paper, 2023). A squamous cell carcinoma that arises from any of the following anatomic sites: lip and oral cavity, nasal cavity, paranasal sinuses, pharynx, larynx, and salivary glands. "In parallel, the role of the SIRPα/CD47 axis has been described in head and neck squamous cell carcinoma (HNSCC)." (PMID 36829496, 2023).
Hemophagocytosis (1 paper, 2023). Phagocytosis by macrophages of erythrocytes, leukocytes, platelets, and their precursors in bone marrow and other tissues. "Therefore, although the loss of the intracellular region of SIRPα may contribute to hemophagocytosis during VL, the extent of the involvement is unclear." (PMID 37111479, 2023).
hemorrhagic fever (1 paper, 2022). An infectious disease caused by certain viruses or bacteria that can damage the walls of tiny blood vessels, making them leak, and can hamper the blood's ability to clot and cause severe, life-threatening illness. "In a relevant research, TRIM2 was found through in vivo experiments in mice to play a unique antiviral role by interacting with SIRPA to block cellular entry of hemorrhagic fever New World arenavirus (NWA)." (PMID 36051486, 2022).
Impaired glucose tolerance (1 paper, 2021). An abnormal resistance to glucose, i.e., a reduction in the ability to maintain glucose levels in the blood stream within normal limits following oral or intravenous administration of glucose. "High-fat diet-fed SIRPα-/- mice exhibit reduced plasma insulin levels and impaired glucose tolerance as compared to wild-type mice, providing in vivo evidence that SIRPα can control insulin secretion in the context of metabolic stress." (PMID 34603322, 2021).
Insulin resistance (1 paper, 2025). Increased resistance towards insulin, that is, diminished effectiveness of insulin in reducing blood glucose levels. "Given the potential role of SIRPA in insulin resistance and inflammation, these existing therapies warrant further exploration for their applicability in DKD treatment." (PMID 40299563, 2025). "Since insulin resistance and chronic inflammation are considered to be potential mechanisms underlying DKD, our findings suggest that SIRPA could have a detrimental effect on DKD." (PMID 40299563, 2025).
ischemia (1 paper, 2024). A hypoperfusion of the BLOOD through an organ or tissue caused by a PATHOLOGIC CONSTRICTION or obstruction of its BLOOD VESSELS, or an absence of BLOOD CIRCULATION. "All Sirpα−/− mice received hindlimb artery ligation to create an ischemia model, the wild-type mice received the same surgery and were used as a control." (PMID 39707436, 2024).
ischemic disease (1 paper, 2024). Lack of blood supply to an area of the body, resulting in impairment of tissue oxygenation. "Accelerating the loss and regain of Sirpα at the exact time-point promises a better recovery from ischemic disease." (PMID 39707436, 2024). "Downregulation of macrophage Sirpα at the early-stage or upregulation of macrophage Sirpα at the late-stage of ischemic disease enhances the therapeutic effect." (PMID 39707436, 2024). "In contrast, increasing Sirpα at the early-stage or decreasing it at the late-stage leads to failure of inducing ischemic disease resilience." (PMID 39707436, 2024). "This study emphasizes the importance of time-point in ischemic disease treatment and introduces Sirpα as a new therapeutic target, and expands our understanding of the underlying mechanism of macrophage polarization facilitated ischemic disease recovery." (PMID 39707436, 2024). "Our results reveal that dynamic regulation of macrophage by Sirpα plays a critical role in alleviating ischemic diseases." (PMID 39707436, 2024). "Although, the role of Sirpα in tumor treatment has been discussed, its possible role in ischemic diseases is largely unknown." (PMID 39707436, 2024). "Downregulation of Sirpα in macrophages at the early-stage of the ischemic disease could promote apoptotic debris clearance." (PMID 39707436, 2024).
lung adenocarcinoma (1 paper, 2023). A carcinoma that arises from the lung and is characterized by the presence of malignant glandular epithelial cells. "Patients with higher expression of SIRPα had worse disease‐free survival (DFS) and overall survival (OS) in lung squamous cell carcinoma (LUSC), but SIRPα had no predictive value in lung adenocarcinoma (LUAD)." (PMID 36419386, 2023).
lung injury (1 paper, 2023). "In LPS-induced acute lung injury, soluble SIRPα promoted phagocytosis of apoptotic neutrophils by bone marrow-derived macrophages." (PMID 37111479, 2023).
lymph node metastasis (1 paper, 2023). "The current findings indicated that SIRPα expression may inhibit the occurrence of lymph node metastasis and thus prolong survival." (PMID 37291116, 2023). "Further analysis revealed that SIRPα expression correlated with free lymph node metastasis, but not with vascular invasion status or distant metastasis." (PMID 37291116, 2023).
meningioma (1 paper, 2023). A generally slow growing tumor attached to the dura mater. "Results revealed that SIRPα was co-expressed with CD68 both in malignant meningioma tissues and mouse subcutaneous xenografts, indicating that the phagocytosis of malignant meningioma cells by macrophages maybe mediate by CD47-SIRPα axis." (PMID 37171006, 2023). "Moreover, we examined the expression of signal regulatory protein-alpha (SIRPα), one of the most important receptor of CD47, in both malignant meningioma tissues and mouse subcutaneous xenografts derived from the human malignant meningioma cell line IOMM-Lee." (PMID 37171006, 2023).
myeloid leukemia (1 paper, 2024). A clonal proliferation of myeloid cells and their precursors in the bone marrow, peripheral blood, and spleen. "CD47, a macrophage checkpoint, has been identified as highly expressed on myeloid leukemia stem cells and acts as a ligand for signal regulatory protein alpha (SIRPα) found on macrophages." (PMID 38191498, 2024).
oral cancer (1 paper, 2016). "After cultured with the conditioned media of oral cancer cells, the expression of SIRPα on THP-1 cells was decreased gradually." (PMID 27793032, 2016). "Our findings provide a new insight into the importance of SIRPα on macrophages in oral leukoplakia and oral cancer progression." (PMID 27793032, 2016). "The current data represented that relative lower expression of SIRPα on macrophages in co-culture assay was correlated with the recruitment and invasion of oral cancer cells, indicating that oral cancer might exploit the macrophages with SIRPα reduction to profit themselves." (PMID 27793032, 2016). "Therefore, SIRPα might be a potential target for oral cancer therapy." (PMID 27793032, 2016). "Hence, SIRPα might play an important role in the progression of OLK and oral cancer, and could be a pivotal therapeutic target in OSCC by regulating the phenotype of macrophages via targeting NF-κB." (PMID 27793032, 2016). "However, the profile of SIRPα expression in OLK and OSCC and the mechanism by SIRPα regulating macrophages or oral cancer cells remain unclear." (PMID 27793032, 2016).
Oral leukoplakia (1 paper, 2016). A thickened white patch on the oral mucosa that cannot be rubbed off. "Our previous study showed that CD47 was up-regulated in oral leukoplakia (OLK) and OSCC, suggesting cancer cells may evade phagocytosis of macrophages through the interaction of CD47 with SIRPα." (PMID 27793032, 2016).
parasite (1 paper, 2023). "Increased soluble SIRPα was also detected in a culture supernatant of macrophages infected with L. donovani in vitro, suggesting the parasite infection promotes ectodomain shedding of SIRPα on macrophages." (PMID 37111479, 2023).
parasitic diseases (1 paper, 2023). "Only a few papers have shown increased serum SIRPα in diseased conditions, and our present study is the first report of increased serum SIRPα in parasitic diseases." (PMID 37111479, 2023). "In addition, we examined if the parasite infection promotes ectodomain shedding of SIRPα on macrophages in vitro." (PMID 37111479, 2023).
periodontitis (1 paper, 2024). An acute or chronic inflammatory process that affects the tissues that surround and support the teeth. "In periodontitis sections, infiltrating leukocytes stained positive for SIRPα." (PMID 39258954, 2024). "However, SIRPα has not been investigated in relationship to periodontitis, an inflammatory condition affecting the tooth supporting tissues." (PMID 39258954, 2024). "The fact that inflammatory stimulation of gingival fibroblasts increased the expression of SIRPα, while an increased expression by gingival fibroblasts in periodontitis tissue in situ could not be detected, is indeed contradictory." (PMID 39258954, 2024).